FOXM1 (forkhead box M1)
Diseases named in the same sentence as FOXM1 in open-access papers (continued):
Sharing a sentence is not in itself a finding about the gene and the disease.
gastric cancer (continued). "In gastric cancer, Twist 1 could bind to the promoter region of FOXM1, and subsequently recruit p300 to induce its mRNA transcription." (PMID 30208972, 2018). "In gastric cancer, FOXM1 can bind to the promoter region of PVT1 and enhance its transcription." (PMID 29244840, 2017). "In gastric cancer, Akt/FoxM1 signaling has been reported played an important role in chemotherapy." (PMID 28784180, 2017). "However, FOXM1 siRNA repressed cell migration and invasion, and also decreased the expression of Cath-D in gastric cancer cells." (PMID 28978107, 2017). "In the next study, we will carry out further studies to identify whether FOXM1 is modulated by other transcription factors, in the progression of gastric cancer." (PMID 28978107, 2017). "Also, overexpression of the SLPI in gastric cancer cells increased the expression of FoxM1 target genes iMMP-2 and MMP-9 and promoted the migration of cancer cells by degrading collagen but FoxM1 was not examined." (PMID 29312532, 2017). "In addition, miR-194 inhibited the epithelial-mesenchymal transition phenotype in gastric cancer cells by targeting FoxM1." (PMID 29163456, 2017). "High FOXM1 expression in gastric cancer significantly induces PVT1 expression." (PMID 29113415, 2017). "This clinical evidence supports the negative association of miR-320a and FoxM1 expression in gastric cancer." (PMID 27086911, 2016). "Overexpression of transcription factor forkhead box protein M1 (FOXM1) mediates resistance to docetaxel-induced apoptosis in gastric cancers, and stathmin correlates with resistance to docetaxel in FOXM1-silenced gastric cancer cells, indicating that stathmin is effective downstream signal of FOXM1." (PMID 27670291, 2016). "Having established up-regulation of FOXM1 protein expression in gastric cancers, we next wanted to test whether we could detect co-upregulation of PLK1." (PMID 26576650, 2015). "In any case, these data generally suggested that the expression of Stathmin could mediate docetaxel resistance in gastric cancer cells after the silence of FOXM1." (PMID 24628949, 2014). "To investigate whether Stathmin is a downstream signalling target of FOXM1 in gastric cancer, we next cotransfected Stathmin promoter–reporter plasmids with FOXM1-overexpressed vectors or FOXM1-siRNA into malignant human gastric cell lines." (PMID 24628949, 2014). "Conversely, Stathmin re-expression could partially attenuate docetaxel-induced cell apoptosis in FOXM1-knockdown gastric cancer cells and decrease their sensitivity to docetaxel as a result of MTT assay." (PMID 24628949, 2014). "Furthermore, when Stathmin was overexpressed in FOXM1-knockdown gastric cancer cells, they became resistant to docetaxel, indicating that the FOXM1–Stathmin axis plays a critical role in docetaxel resistance." (PMID 24628949, 2014). "It has been mentioned that FOXM1 was overexpressed in about 68–78% of gastric cancers." (PMID 24628949, 2014). "Moreover, when we attenuated FOXM1 expression with FOXM1 inhibitor thiostrepton, docetaxel resistance in gastric cancers was found to be reversed, simultaneously with the down-regulation of FOXM1 and Stathmin." (PMID 24628949, 2014). "Through the inhibition of FOXM1, it is possible that docetaxel resistance can be reversed, and FOXM1 might be a new therapeutic target in docetaxel-resistant gastric cancer." (PMID 24628949, 2014). "Moreover, through cox proportional hazard model, FOXM1 expression levels were significantly identified as an independent prognostic factor for survival duration in gastric cancer patients (P < 0.01)." (PMID 24628949, 2014).
gastric cancer (continued). "Furthermore, we performed an immunohistochemical analysis of FOXM1 and Stathmin proteins in 103 gastric cancer samples." (PMID 24628949, 2014). "As a result, FOXM1 overexpression was shown to mediate resistance to docetaxel in gastric cancers." (PMID 24628949, 2014). "In this study, we intend to investigate the correlation between FOXM1 expression and chemotherapy response to docetaxel in gastric cancer cells and further explore its possible mechanism, trying to provide a support to chemotherapy choice for gastric cancer patients in clinical practice." (PMID 24628949, 2014). "Next, we examined whether Stathmin and MCAK are the downstream targets of FOXM1 in conferring docetaxel resistance in gastric cancer cells." (PMID 24628949, 2014). "Through the inhibition of FOXM1, docetaxel resistance can be reversed, and thus FOXM1 could be a new therapeutic target in docetaxel-resistant gastric cancer." (PMID 24628949, 2014). "These hypotheses were further provided by our results, which showed that FOXM1 is an independent prognostic factor in gastric cancer." (PMID 24004449, 2013). "Based on these results, it is considerately that FOXM1 should be combined with the tumor size, T stage and TNM stage for predicting the prognosis of gastric cancer, and further studies should focus on exploring the mechanism of FOXM1 on promoting the adverse progression of advanced gastric cancers." (PMID 24004449, 2013). "Therefore, further studies should be focused on the anti-tumor function of FOXM1 inhibitors, especially in docetaxel-resistant gastric cancer." (PMID 24004449, 2013). "Although FOXM1 has been revealed to mediate promotion of human gastric cancer angiogenesis, growth, and metastasis, the clinical significance of FOXM1 overexpression in gastric cancer is still little explored yet." (PMID 24004449, 2013). "When we attenuated FOXM1 expression with FOXM1 inhibitor thiostrepton, docetaxel resistance in gastric cancers could be reversed, simultaneously with the down-regulation of FOXM1." (PMID 24004449, 2013). "Moreover, shown to mediate docetaxel resistance in gastric cancers, FOXM1 was revealed to interfere in microtubule polymerization after the treatment of docetaxel in our research." (PMID 24004449, 2013). "In addition, we investigated the relationship between overexpression of FOXM1 and docetaxel resistance in gastric cancer cells, trying to provide a support to its clinical significance in clinical practice." (PMID 24004449, 2013). "Additionally, knockdown of endogenous FoxM1 expression attenuates the proliferative effect of Twist 1, suggesting that FoxM1 is essential for the roles of Twist 1 in gastric cancer cells." (PMID 24204899, 2013). "In gastric cancer (GC) and nasopharyngeal carcinoma, FOXM1 induces the characteristics of CSCs and enhances the tumorigenicity." (PMID 38561775, 2024). "Furthermore, in gastric cancer, FOXM1 is related to proliferation and invasion, and when it is co-expressed with hTERT it might be involved in cell-cycle-related pathways and positively related to advanced stages and poor outcomes." (PMID 39228892, 2024). "Interestingly, patients with gastric cancer with high FOXM1/low RNF112 displayed the shortest survival, indicating that the combination of the 2 indices could predict the survival of patients more sensitively." (PMID 37288663, 2023). "Furthermore, RNF112 exhibited the strongest negative association with FOXM1 in 5 independent gastric cancer cohorts derived from the NCBI Gene Expression Omnibus (GEO) and TCGA." (PMID 37288663, 2023). "Moreover, FOXM1 is a known downstream factor of the Akt signaling cascade, and inactivation of the Akt/FOXM1 signaling pathway may suppress the proliferation and metastasis of gastric cancer cells." (PMID 35906389, 2022). "Moreover, PARPBP has been suggested to be activated by FOXM1 in gastric cancer cells." (PMID 32133296, 2020).
gastric cancer (continued). "It was also reported that FOXM1 could promote gastric cancer cell migration and invasion." (PMID 31949481, 2020). "Therefore, those predicted inhibitors which could reverse the gene expression patterns of the FOXM1+PLAU+ subgroup may worth exploring as new therapeutic options for gastric cancer." (PMID 31949481, 2020). "Besides, the researchers found FoxM1 could participate in regulating the telomerase activity in gastric cancer cells." (PMID 29554906, 2018). "Thus, our study indicated that FOXM1 and Cath-D might be potential and useful targets for gastric cancer patients, especially patients with metastasis." (PMID 28978107, 2017). "In the previous study, we assumed that FOXM1 might be a potential cancer inducer in gastric cancer." (PMID 28978107, 2017). "Thus, we analyzed the expression of miR-320a and FoxM1 in human gastric cancer species." (PMID 27086911, 2016). "Overall, these findings verified that FOXM1 directly targeted and up-regulated the microtubule-destabilizing protein Stathmin, and then prevented the tubulin polymerization, eventually mediated the resistance to docetaxol-induced apoptosis in gastric cancer cells." (PMID 24628949, 2014). "Moreover, compared with those FOXM1-knockdown cells, the transfection of pcDNA3.1-Stathmin was found to be able to slightly elevate the expression levels of FOXM1 in gastric cancers, in addition that the FOXM1 protein level is also increased after pcSathmin transfected." (PMID 24628949, 2014). "Furthermore, the overexpressed FOXM1 could simultaneously induce gastric cancer angiogenesis and progression through regulating the level of VEGF (vascular endothelial growth factor) gene expression and correlating with MVD (microvessel density)." (PMID 24004449, 2013). "Moreover, FoxM1 is also repressed by miR-370 in gastric cancer cells, suggesting that further studies are required to investigate whether Twist 1 could cooperate these regulatory pathways." (PMID 24204899, 2013). "Therefore, our results uncover a previous unknown Twist 1/FoxM1 regulatory pathway, which may help to understand the mechanisms of gastric cancer proliferation." (PMID 24204899, 2013). "FOXM1 can be a useful marker for predicting patients’ prognosis and monitoring docetaxel response, and might be a new therapeutic target in docetaxel resistant gastric cancer." (PMID 24004449, 2013). "Another ETS family member, SAM, pointed domain containing ETS transcription factor (SPDEF) promotes the expression of transcription factor Forkhead Box M1 (FOXM1) by directly binding its promoter, which contains a core GGAT sequence, in gastric cancer cells." (PMID 41425714, 2025). "They focused on Forkhead box M1 (FOXM1), which is linked to tumor cell cycle, drug resistance, and tumor immune escape, and reported that FOXM1 affected PD‐L1 levels through the Notch pathway, thereby promoting gastric cancer (GC) progression." (PMID 41026775, 2025). "A positive correlation between FOXM1 and VEGF expression has been observed in various cancers, including breast, brain, and stomach cancers." (PMID 39594778, 2024). "Increased expression of FOXM1 in cancer has been observed in various tumor types, including EAC and gastric cancer." (PMID 38373993, 2024). "We then evaluated the prototype thiopeptide, thiostrepton, for anticancer properties, finding that thiostrepton decreased FOXM1 expression in AGS cells and inhibited the growth of MKN-45 and AGS gastric cancer epithelial cell lines." (PMID 38014984, 2024). "To assess the potential significance of RNF112 in gastric cancer, we examined the downstream mRNA networks of RNF112 and FOXM1 by RNA-Seq." (PMID 37288663, 2023). "Thus, the RNF112/FOXM1 axis not only could be considered a potential biomarker for predicting patients’ prognosis but also could be developed as a therapeutic target to combat gastric cancer." (PMID 37288663, 2023).
gastric cancer (continued). "In gastric cancer, miR-361-5p can suppress chemoresistance of SGC-7901 and MKN-28 cells through inhibition of the expression of FOXM1." (PMID 36275636, 2022). "Tanshinone IIA proved to suppress gastric cancer cells growth by the down-regulation of STAT3 and FOXM1 expression." (PMID 35897965, 2022). "In order to increase the bioavailability of genistein, 7-difluoromethoxyl-5,4′-di-n-octylygenistein (DFOG) was synthesized and this compound was shown to downregulate FOXM1 expression in EOC and gastric cancer cells." (PMID 34205406, 2021). "Evidence suggests that FOXM1 promotes GC cell migration, invasion, and EMT and is an independent factor affecting the prognosis of gastric cancer." (PMID 33407516, 2021). "For example, miRNA-194 suppresses gastric cancer cell migration, invasion and epithelial- mesenchymal transition (EMT) by downregulating FoxM1." (PMID 32284739, 2020). "FoxM1 also played a vital role in promoting angiogenesis and lymph node metastasis by regulating the expression of MMP in gastric cancer." (PMID 29554906, 2018). "Knockdown of FOXM1 suppresses the EMT and expression of VEGF in gastric cancer cells, which resembles the phenotype observed in PAX8-overexpressing gastric cancer cells." (PMID 30021604, 2018). "Another study found that FoxM1 is a key downstream effector that regulates the MET signaling pathway, resulting in DNA damage in gastric cancer cells." (PMID 30580327, 2018). "We further checked the involvement of forkhead box M1 (FOXM1), a ubiquitously expressed oncogene that can facilitate gastric cancer progression, in the action of PAX8." (PMID 30021604, 2018). "Thus, FOXM1 may be recommended as a potential therapeutic target for gastric cancer patients." (PMID 28978107, 2017). "In this study, we investigated the correlation between the expression of transcription factor forkhead box protein M1 (FOXM1) and chemotherapy response to docetaxel in gastric cancer, the possible mechanism for which was further explored." (PMID 24628949, 2014). "Additionally, shown to mediate docetaxel resistance in gastric cancers by our research, FOXM1 was revealed to alter microtubule dynamics in response to the treatment of docetaxel, and the drug resistance could be reversed with FOXM1 inhibitor thiostrepton treatment." (PMID 24004449, 2013). "Therefore, FOXM1 can be a useful marker for predicting patients’ prognosis and monitoring docetaxel response, which might be a new therapeutic target in docetaxel resistant gastric cancer." (PMID 24004449, 2013). "Gli-1 is known to induce expression of proliferative genes such as cyclin D2, FOXM1 and the ras-ERK pathway and to reduce expression of cell cycle repressor p21/CIP1 in gastric carcinoma cell lines." (PMID 17505514, 2007). "In DDP-resistant gastric cancer cells, overexpressed METase could downregulate the expression of lncRNA HULC, thus decreasing the protein level of FoxM1 and suppressing autophagy and cisplatin resistance." (PMID 38927012, 2024). "Moreover, it was identified by a dual luciferase reporter assay that KLF11 binds directly with the promoters of specific gastric cancer stemness-related molecules, including SOX2 and FOXM1." (PMID 38025523, 2023). "Mechanistically, KMT2A activated the translocation of β-catenin into the nucleus of gastric cancer cells, and then, β-catenin served as a coactivator of KLF11, which promoted the expression of specific gastric cancer stemness-related molecules, including SOX2 and FOXM1." (PMID 38025523, 2023). "In gastric cancer, lncRNA TRPM2-AS enhanced radioresistance via miR-612/FOXM1 axis." (PMID 35600868, 2022). "miR-4521 inhibited by the ETS proto-oncogene 1 (ETS1) targets both insulin = like growth factor 2 (IGF2) and forkhead box M1 (FOXM1) to inhibit Akt/GSK3β/Snai1 pathway proteins, and achieves inhibition of gastric cancer cell metastasis in hypoxia-induced conditions." (PMID 35805066, 2022).
gastric cancer (continued). "Moreover, in the gastric cancer cell line SGC7901, tanshinone IIA down-regulated the expression of matrix metalloproteinase 2 (MMP-2), MMP-9, and FOXM1." (PMID 35897965, 2022). "Likewise, a previous report indicated that FoxM1 overexpression enhanced the number of CD4+CD8+ Treg cells and Ki67 protein levels, to strengthen the immune escape of gastric cancer." (PMID 36301031, 2022). "Similarly, FoxM1 overexpression was related to increased TGF‐β levels, enhanced cellular resistance to drugs, and sabotaged immunoreaction in gastric carcinoma." (PMID 36301031, 2022). "Additionally, FOXM1 was also shown to interact with lncRNA, PVT1 and promote tumor growth and metastasis in gastric cancer." (PMID 33680951, 2020). "As mentioned, FOXM1 and PLAU are indicators of poor prognosis with shorter OS and RFS time in the gastric cancer, and results from microarray also indicated FOXM1+PLAU+ related genes are enriched in TGF-beta, DNA repair, MAPK and drug resistance signaling pathways." (PMID 31949481, 2020). "Tan IIA could down-regulate FOXM1, MMP-2, and MMP-9 expression in gastric cancer SGC7901 cell line, resulting in the suppression of proliferation and migration in a dose-dependent way." (PMID 32265690, 2020). "Zhang and his colleagues showed that Tan IIA could suppress gastric cancer cells growth by down-regulating STAT3 and FOXM1 expression." (PMID 32265690, 2020). "Additionally, the expression of YAP1, FOXM1, KRAS, and BATF genes were decreased in gastric cancer cells by treatment of UA." (PMID 31547587, 2019). "More importantly, we found that CCAL could bind to miR-149, suppress the translation of Fork head box M1 (FOXM1), and subsequently promote metastasis in gastric cancer." (PMID 30250169, 2018). "To date, the mechanisms of FOXM1 in modulating the invasion and metastasis of gastric cancer cells have not been elucidated." (PMID 28978107, 2017). "Thus, high expression of FOXM1 and PVT1 form a positive feedback loop that promotes gastric cancer proliferation and metastasis." (PMID 29113415, 2017). "Firstly, our observations showed that the expression of FOXM1 was obviously higher in gastric cancer tissues compared with that in adjacent non-tumor tissues." (PMID 28978107, 2017). "SLPI promoted migration, invasion and metastasis of gastric cancer cells by increasing expression of MMP-2 and MMP-9 genes, and the latter could have been targeted by transcriptional factor FoxM1." (PMID 29312532, 2017). "Nevertheless, this inhibitory effect on FOXM1 has not been analyzed for human gastric cancer so far." (PMID 24004449, 2013). "However, only the tumor size, T stage, FOXM1 expression and TNM stage were verified to be independent prognostic factors for the survival in gastric cancer patients after multivariate analysis (P < 0.05)." (PMID 24004449, 2013). "Future studies may compare Foxm1 expression and gastric cancer rates in H. pylori-colonized patients with and without concurrent thiopeptide-positive C. acnes colonization." (PMID 38014984, 2024). "However, the existence of FOXM1 in circulating exosomes and the role of exosome FOXM1 in gastric cancer (GC) were not clear." (PMID 33971889, 2021). "Thus, FOXM1 and PLAU may function coordinately to promote gastric cancer progression and therapeutic resistance through multiple signaling pathways." (PMID 31949481, 2020). "PVT1 directly binds to FOXM1 and enhances its stability, and FOXM1 in turn initiates PVT1 expression through binding to the PVT1 promoter, thus forming a feedback loop between PVT1 and FOXM1 that plays a critical role in promoting gastric cancer cell proliferation and invasion." (PMID 31497532, 2019). "However, the role and mechanism of FOXM1 has not been elucidated completely in gastric cancer." (PMID 28978107, 2017). "The potential therapy capacity of FOXM1 and PLAU is not limited in the gastric cancer, also suitable for the NSCLC." (PMID 31949481, 2020).
gastric cancer (continued). "Similarly, OS was not significantly different in patients with advanced gastric cancer treated with multiple peptides (DEPDC1, URLC10, FoxM1, Kif20A, and VEGFR1) who were A24(+) compared with A24(–)." (PMID 38993370, 2022).